SMLR1 (small leucine rich protein 1)
Tractability: Antibody: UniProt predicts a signal peptide or a membrane-spanning region. PROTAC: ubiquitination databases record sites on it.
Gene: Protein-coding gene on chromosome 6 (130,827,406 to 130,837,135, forward strand). Ensembl gene ENSG00000256162.
Subcellular location: Membrane
Gene Ontology:
Molecular function: protein binding
Cellular component: membrane
Genetic constraint (gnomAD): Loss-of-function variants: 4 observed, 8.2 expected, observed/expected ratio (o/e) 0.49, 90% interval 0.24 to 1.12. That is too few expected variants to judge how well the gene tolerates losing a copy. Missense variants: 126 observed, 129.11 expected, observed/expected ratio (o/e) 0.98, 90% interval 0.84 to 1.13. Synonymous variants: 55 observed, 56.13 expected, observed/expected ratio (o/e) 0.98, 90% interval 0.79 to 1.23.
Homologues: Orthologues: chimpanzee SMLR1 (100% identical), macaque SMLR1 (87% identical), pig SMLR1 (65% identical), mouse Smlr1 (41% identical), rat Smlr1 (39% identical).
Diseases named in the same sentence as SMLR1 in open-access papers:
SMLR1 is named in the same sentence as 4 diseases in open-access papers, as found by Europe PMC text mining. Sharing a sentence is not in itself a finding about the gene and the disease. The quoted sentences say what the papers report.
colorectal cancer (1 paper, 2024). A primary or metastatic malignant neoplasm that affects the colon or rectum. "In this inaugural issue of Cancer Heterogeneity and Plasticity, Wong and colleagues present novel roles of small leucine-rich protein 1 (SMLR1) in colorectal cancer liver metastasis (CRLM)." (PMID 39324019, 2024).
cancer (1 paper, 2024). A tumor composed of atypical neoplastic, often pleomorphic cells that invade other tissues. "The elucidation of SMLR1’s role in immune evasion and metastasis contributes valuable insights into cancer cell plasticity and reprogramming." (PMID 39324019, 2024). "Future studies could broaden the scope of clinical relevance by examining SMLR1 upregulation in other metastatic sites and cancer types." (PMID 39324019, 2024). "Notably, SMLR1 upregulation was observed specifically in the CRC liver metastases but not in CRC metastases in other tissues such as the peritoneum, suggesting a context-dependent interaction between cancer cells and the liver microenvironment that facilitates metastasis." (PMID 39324019, 2024).
tumor (1 paper, 2024). "By demonstrating that SMLR1 is upregulated in CRLM and interacts with tumor-associated macrophages (TAMs) via MRC1 (CD206) and SIGLEC1 (CD169), this research unveils a novel mechanism of immune evasion and tumor progression." (PMID 39324019, 2024).
SMLR1 also shares sentences with these, for which no sentence is quoted: metastasis (1 paper).